CDC20 (cell division cycle 20)
Diseases named in the same sentence as CDC20 in open-access papers (continued):
Sharing a sentence is not in itself a finding about the gene and the disease.
tumor (continued). "We also found that these anti-tumor effects on RCC cells caused by CYP1B1 depletion may be due to alteration of CDC20 and DAPK1 expression based on gene microarray and confirmed by real-time PCR." (PMID 26626260, 2015). "Although bioinformatics analyses implicated CDC20 in cell cycle regulation and immune modulation, these findings lack comprehensive experimental validation, as the study relied on only two cell lines and omitted in vivo models to assess CDC20’s role in a complex tumor microenvironment." (PMID 41374402, 2025). "A non-coding variant upstream of the CDC20 promoter leads to down-regulation of CDC20 expression and up-regulation of a more proliferative and melanocytic transcriptional program that may aid in accelerating tumor growth." (PMID 38030698, 2023). "WGA staining indicated that DOX administration caused cardiomyocyte atrophy, whereas cardiomyocytes size increased after CDC20 overexpression compared with the DOX + tumor group." (PMID 40045239, 2025). "Mechanistic investigations demonstrated that CDC20 promotes tumor invasion and growth by modulating mitosis and cell cycle progression, while also influencing the tumor microenvironment through immune cell regulation." (PMID 41374402, 2025). "Collectively, these findings position CDC20 as a key driver of tumor aggressiveness and an indicator of unfavorable prognosis." (PMID 41374402, 2025). "CDKN2A and CDC20 expressions correlated significantly with stage and grade, while TGFB1, CDKN2A, and CDC20 were highly expressed in proliferative tumor cells." (PMID 40256740, 2025). "Spearman correlation analysis revealed that CDC20 expression was positively correlated with the number of tumor cells in the spot." (PMID 39895786, 2025). "Conversely, deletion of the rotor component regulating inhibition of the CDC20 checkpoint promotes tumor development." (PMID 41374402, 2025). "CDC20 was localized by immunofluorescence analysis in tumor cell lines, and its expression level was determined by immunohistochemistry on tissue chips." (PMID 39895786, 2025). "The results demonstrate that BC patients have an elevated CDC20 expression in tumor tissues compared with the adjacent normal tissue." (PMID 39061186, 2024). "A tumor xenograft model was conducted in BALB/c-nu/nu mice to confirm the function of CDC20 in vivo, confirming the in vitro results." (PMID 39125953, 2024). "In summary, targeting CDC20 exacerbates the heightened levels of DNA damage induced by radiation or chemotherapy, thereby augmenting the sensitivity of tumor treatment." (PMID 39125953, 2024). "The fold-change results for CDC20 gene expression showed an average 10.54-fold increase in the low tumor grade group and a 16.1-fold increase in the high tumor grade group." (PMID 39795587, 2024). "In summary, the fold increase in CDC20 gene expression was found to be significantly higher in the patient group with a high tumor grade." (PMID 39795587, 2024). "We also found a significant positive correlation between overexpressed CDC20 and tumor purity and many immune cells; the finding suggests that CDC20 plays a fundamental role in controlling tumor immunity and consequently influences BC prognosis." (PMID 39061186, 2024). "Survival data were used to compare various patient subgroups, including tumor stage (pTa, pT1, and pT2), grade (LG and HG), and gene expression levels of CDC20 and CCNB1, with respect to overall survival." (PMID 39795587, 2024). "Previous studies have revealed an oncogenic role for Cdc20 through mediating a majority of tumor suppressor destruction." (PMID 39401430, 2024). "Many studies have shown that the oncogene CDC20 is significantly overexpressed in most tumor types, including BC, and its overexpression has been suggested as a biomarker of poor outcomes." (PMID 39061186, 2024). "To elucidate the potential mechanistic role of CDC20 in tumor malignancy, we transfected H1299 and H1975 cells with siRNA." (PMID 39114311, 2024).
tumor (continued). "In TNBC human samples, CDC20 upregulation was found to augment tumor cell growth, migration, metastasis, and decreased overall survival." (PMID 39061186, 2024). "Targeting CDC20 can enhance the radiosensitivity of tumor cells, but the function and mechanism of CDC20 on DNA damage repair response remains vague." (PMID 39125953, 2024). "The finding suggests that CDC20 plays a fundamental role in controlling tumor immunity and consequently influences BC prognosis." (PMID 39061186, 2024). "This study reveals a significant positive correlation between overexpressed CDC20 and tumor purity and many immune cells; the finding suggests that CDC20 plays a fundamental role in controlling tumor immunity and consequently influences BC prognosis." (PMID 39061186, 2024). "The results showed that CDC20 expression had a significant positive correlation with tumor grade (r = 0.284, p = 0.038), indicating that higher CDC20 expression was associated with higher tumor grades." (PMID 39795587, 2024). "We investigated the differential expression of the genes targeted by CDC20 and its role as either tumor suppressor or promoter." (PMID 39061186, 2024). "While CDC20 appears to be more closely associated with tumor grade, CCNB1 is more strongly associated with tumor stage and survival outcomes." (PMID 39795587, 2024). "CDC20 gene expression was significantly higher in the high tumor grade patient group than in the low tumor grade group." (PMID 39795587, 2024). "Two genes (CCNB2, CDC20) were found to be related to necrosis, inflammation, hyperplasia, and tumor." (PMID 36820589, 2023). "Multiple studies have demonstrated that CDC20 plays an important role in promoting and maintaining tumor cell proliferation." (PMID 37682144, 2023). "The CDC20 inhibitor apcin, which blocked the CDC20-related substrates binding to CDC20, has been proved in several researches to have effect on tumor cell growth and drug sensitivity." (PMID 36882855, 2023). "Meanwhile, CDC20 functioned as the prognostic factor in some tumors, and was closely related to the clinicopathological characteristics of tumor patients." (PMID 36882855, 2023). "Some researchers have demonstrated that CDC20 also regulates apoptosis, immune microenvironment, and tumor angiogenesis." (PMID 37682144, 2023). "Above all, depletion of CDC20 enhances the anti-tumor immunity and synergistic effects with α-PD-1 mediated by GSDME." (PMID 37528490, 2023). "To gain further insight into the role of CDC20 in anti-tumor immunity, and we generated multiple TRAMP-C2 cell lines with various independent shRNAs constructs targeting CDC20 or GSDME." (PMID 37528490, 2023). "Consistently, the features for suppression of anti-tumor immunity were dominantly elevated in the CDC20-high group, such as BTLA, CTLA4, CD4, ITGAM, C4B, CD163, and CD206." (PMID 37528490, 2023). "Eight hub genes (CDK1, EGFR, UBC, MYC, CCNB1, RHOB, CDC6, and CDC20) have tumor suppressor functions, while five hub genes (CDK1, EGFR, FYN, UBC, and CCNB1) are protein kinases as well." (PMID 35632527, 2022). "We and others have observed that elevated CDC20 expression was often detected in tumor tissues, including breast, colorectal, lung, bladder, cervical, liver, ovarian, and prostate cancers." (PMID 35954396, 2022). "The APC/C either has an oncogenic function after binding to its co-activator Cdc20, or works as a tumor suppressor when bound to Cdh1." (PMID 35832196, 2022). "A pairwise boxplot was also analyzed, suggesting that tumor samples almost have a higher expression of CDC20 than normal ones (P < 0.001)." (PMID 35800227, 2022). "Previous findings have discovered that CDC20 plays a significant function in the maintenance of tumor stem cell properties." (PMID 35816352, 2022). "Randall King’s group has developed several CDC20 small molecule inhibitors and tested their role in tumor growth inhibition in various preclinical models." (PMID 35954396, 2022).
tumor (continued). "The role of CDC20–hnRNPU in tumor progression and drug resistance was examined by CCK-8 cell survival and clonogenic assays." (PMID 35954396, 2022). "Logistic regression analysis showed that the high expression of CDC20 was related to gender, tumor grade, clinical stage, T stage, M stage, and N stage." (PMID 35800227, 2022). "In vivo models confirmed that Apcin treatment dampened CDC20 expression and inhibited the tumor growth in NOD/SCID mice bearing OCI-Ly10 xenografts." (PMID 35490245, 2022). "In summary, CDC20 is involved in a number of biological and tumor-related functions, that deserve further investigation in the field of hematological malignancies." (PMID 35490245, 2022). "The expression level of CDC20 in tumor tissue was significantly higher than that in normal kidney tissue." (PMID 35800227, 2022). "We then investigated the expression of PAI1, CDC20, and p21, the newly identified molecules participating in HBx-induced carcinogenesis, in the tumor tissue of the SB mice." (PMID 35223517, 2022). "And beyond that, CDC20 expression was also assessed to be significantly correlated with tumor status and patient age." (PMID 35622386, 2022). "Our study supports the evidence that CDC20 is an oncogene of BC and promotes tumor growth and metastasis." (PMID 36123926, 2022). "Then we can find there are 65 “good genes” among them, and most of 65 “good genes” are negatively correlate with tumor stage, while the only 4 “bad genes” (CDC20, CDCA3, FBXL6, UBE2C) are positively correlate with tumor stage." (PMID 34093816, 2021). "CDC20 interacts with the anaphase-promoting complex/cyclosome in cell cycle and involves in tumor progression." (PMID 34491228, 2021). "The top 100 CDC20-correlated genes in TCGA tumor tissues, normal tissues, and GTEx database, as well as the gene encoding Cdc20-binding proteins according to experimental evidence using the STRING tool, were analyzed by the Venn diagram." (PMID 34527589, 2021). "Further survival analyses, ROC curve analysis and representative image analysis, selected 5 hub genes, including CDK1, CDC20, CCNB1, CENPF, and MAD2L1, that were associated with early diagnosis, tumour stage, and poor outcomes of HCC." (PMID 34603487, 2021). "For other genes, AURKA, PTTG1, CDC20, SLC7A5, E2F8, TPX2, and TUBA4A, high expression in the high-risk group was linked to tumour growth and metastasis." (PMID 34131308, 2021). "CDC20 knockdown has been shown to contribute to G2/M arrest, inhibiting tumor cell cycle progression." (PMID 33718368, 2021). "ISG15, CDC20, TTK, and NCAPG expression showed positive correlations with tumor mutational burden and neoantigen load in BC patients." (PMID 34733851, 2021). "Knockdown of CDC20 via small interfering RNA (siRNA) inhibits the growth of the tumor cells, leads to the accumulation of the cells in the G2/M-phase, and improves the cytotoxicity of paclitaxel." (PMID 34307447, 2021). "In this study, we assessed the expression level of CDC20 in 60 paired WT tissues and corresponding non-tumor samples." (PMID 34513754, 2021). "In UCEC, the abundance of S41 phosphorylated Cdc20 was positively correlated with the increase of tumor pathological grade." (PMID 34527589, 2021). "CDC20 plays a key role in apoptosis and promotes tumor development by mediating specific signaling pathways." (PMID 34753395, 2021). "Western blot analysis of tumor tissues showed that irradiation combined with CDC20 inhibition resulted in upregulated pro-apoptosis protein Bax and downregulated anti-apoptosis protein Bcl-2 33-35." (PMID 34512169, 2021). "Not only using in-silico analysis, the expression levels of CDC20 in CCA cell lines as well as the investigation of the anti-tumor activity of novel potential targeted drugs against CCA cells were compared with the standard chemotherapy, gemcitabine." (PMID 33777535, 2021).
tumor (continued). "In order to reduce the heterogeneity of tumor tissues, and to further confirm localization of CDC20 in immune cells, we included and analyzed three single-cell RNA-seq (scRNA-seq) datasets, GSE98638, GSE125449, GSE140228_10X and GSE140228." (PMID 34512169, 2021). "Here, we reported that knockdown of CDC20 significantly inhibits the tumor growth in C57BL/6J mice, which was consistent with our previous findings in the immune infiltration analysis." (PMID 34527589, 2021). "Previous studies reported high levels of CDC20 in multiple malignancies and it participates in tumor generation and progression of tumor." (PMID 34512169, 2021). "The abundance of Cdc20 was further validated at transcriptional and translational levels with a publicly available dataset and clinical tumor tissues." (PMID 34527589, 2021). "In order to study the role of CDC20 in HCC, we analyzed the CDC20 mRNA levels in tumor tissues and non-tumor tissues of HCC patients." (PMID 34512169, 2021). "After a long-term culture for 3–4 months, CDC20-knockdown cells in acidic medium showed a strong tumor formation ability by subcutaneous injection into mice that is similar to that of tumor cells." (PMID 32322666, 2020). "To investigate the relationship between CDC20, ASPM, and tumour immunity, we analysed the relationship between CDC20, ASPM, and immune cell infiltration via the TIMER website." (PMID 32047816, 2020). "While bound to CDC20, it acts in an oncogenic fashion and promotes tumor development; however, when bound to CDH1, the APC displays many tumor suppressive effects." (PMID 32805721, 2020). "Reducing CDC20 expression significantly increased the inhibitory effects of gamma-rays (10 Gy or 15 Gy) on HCT116 tumor growth." (PMID 32932732, 2020). "The potential role that CDH1 plays in cell biology and tumor development is different from CDC20, as it appears to act as a tumor suppressor." (PMID 32805721, 2020). "Abnormal expression of MAD2 and CDC20 was reported to induce tumor cell aneuploidy in various malignancies." (PMID 32066746, 2020). "SIRT2 has been shown to provide anti-tumor potential by deacetylating both CDC20 and CDH1 to promote their recruitment to the APC and cell cycle progression." (PMID 32805721, 2020). "Up-regulation of cell division cycle 20 (CDC20) in tumor tissues can be used to predict worse overall survival in HCC patients." (PMID 32046048, 2020). "The dysfunction of CDC20 can contribute to poor differentiation, tumor aneuploidy and poor prognosis in multiple cancer, including BC." (PMID 32677673, 2020). "Given the previously reported role of Cdc20 in tumor progression and resistance against anti-mitotic drugs, development of CP5V potentially provides a novel approach for anti-mitotic therapy." (PMID 31669221, 2019). "CDC20 regulates cell cycle and was recognized as an oncogenic role in tumorigenesis and tumor progression." (PMID 31106147, 2019). "In conclusion, the up-regulation of BUB1B, CCNA2, CDC20, CDK1, and WEE1 in tumor tissues are associated with worse OS and DFS in PDAC and is correlated with advanced tumor stage and tumor development." (PMID 30765611, 2019). "Results from recent TCGA (The Cancer Genome Atlas) and pathological studies have demonstrated a pivotal oncogenic role for Cdc20-APC/C in tumor progression as well as drug resistance." (PMID 31669221, 2019). "Results from recent TCGA and pathological studies have demonstrated a pivotal oncogenic role for Cdc20-APC/C in tumor progression as well as drug resistance." (PMID 31669221, 2019). "Immunohistochemistry (IHC) analysis showed that CP5V dramatically decreased Cdc20 expression in the 4T1 xenograft tumor." (PMID 31669221, 2019). "Liposomes with diameters of 160–180 nm functionalized with RGDK-PEG lipopeptide carrying encapsulated siRNA targeted to the cell cycle regulator CDC20 were able to target tumor and tumor endothelial cells via integrin α5β1 when tested in vitro." (PMID 30241287, 2018).
tumor (continued). "Mechanistically, curcumin exerts its anti-tumor functions through down-regulation of Cdc20 expression in PC cells." (PMID 28165402, 2017). "Collectively, our results demonstrate that Cdc20 impairs the tumor suppressive function of SMAR1 and thereby increases malignancy, at least in part." (PMID 28617439, 2017). "In line with this, over-expression of Cdc20 decreased rottlerin-induced cell growth inhibition and apoptosis, whereas down-regulation of Cdc20 by its shRNA promotes rottlerin-induced anti-tumor activity." (PMID 27626499, 2016). "CDC20 is highly expressed in various types of human tumours and studies have shown depleting endogenous CDC20 leads to induction of apoptosis." (PMID 26292153, 2015). "At the same time, CDC20 was also significantly downregulated in the tumor xenografts from the nude mice treated with 331 (10 mg/kg, 40 mg/kg, 80 mg/kg)." (PMID 26153143, 2015). "Concordant with the decrease in tumor growth, we found after TIC transduction with shCDC20, CDC20 knockdown caused loss of TICs in the S, M and G2 cell cycle phases and accumulation in the G1 phase." (PMID 25938542, 2015). "The efficacy of DsiRNA against CDC20 was subsequently assessed in a xenograft model, which indicated a reduced tumor growth as a result of CDC20 DsiRNA therapy." (PMID 25763370, 2015). "Animals bearing TICs expressing shCDC20 showed significantly reduced tumor formation and increased survival relative to control tumors bearing TICs expressing control shRNA, supporting CDC20 as necessary to maintain the tumorigenic potential of TICs." (PMID 25938542, 2015). "We analyzed five patients with the tumor located at different part of the pharynx and found significant increase in cell cycle regulatory CDC20 and MCM2 genes in the tumor when compared with healthy tissue (p = 0.0467and p = 0.0438, respectively)." (PMID 25575813, 2015). "Higher CDC20 expression significantly correlated with advanced tumor stage, poor pathologic differentiation and unfavorable prognosis in locally advanced and advanced clinical stages." (PMID 23758705, 2013). "Furthermore, we identified CDC20 as the upstream regulator of PBRM1, which provides a novel viewpoint for CDC20 to influence tumor immunity." (PMID 39656940, 2025). "•CDC20 silencing inhibits tumor cell proliferation, migration, and invasion in vitro." (PMID 40688701, 2025). "However, DOX administration led to an increase in cardiac inflammatory aggregates and vacuolation compared with those in the tumor group, whereas CDC20 overexpression suppressed these effects of DOX." (PMID 40045239, 2025). "Importantly, Cox regression models revealed that risk scores based on the expression of CDC20, KIF20A and PTTG1 were independent prognostic variables than indices of tumor grade or IDH‐mutant status." (PMID 40047299, 2025). "Experimental validation confirmed the tumor-promoting role of CDC20 in BCa cells." (PMID 41374402, 2025). "Conversely, Plod2, Cdc20, and Cct5 genes were significantly upregulated in tumor tissues." (PMID 40018995, 2025). "Furthermore, in the GSE10927-19750, GSE10927, and GSE19750 cohorts, CDC20 exhibited significantly elevated expression levels in tumor tissues relative to normal tissues." (PMID 40688701, 2025). "In a xenograft tumour model, omaveloxolone decreased tumour volume and CDC20 expression." (PMID 40439120, 2025). "Previous studies have shown that CDC20 is significantly upregulated in tumor tissues." (PMID 40045239, 2025). "The influence of CDC20 on DOX-induced tumor inhibition was assessed in tumor-bearing mice." (PMID 40045239, 2025). "Next, we examined the protein expression of CDC20 in tumor tissues." (PMID 39895786, 2025).